MYC (MYC proto-oncogene, bHLH transcription factor)
Diseases named in the same sentence as MYC in open-access papers (continued):
Sharing a sentence is not in itself a finding about the gene and the disease.
cancer (continued). "However, in cancer cells, the half-life of MYC is prolonged due to abnormal post-translational modifications, resulting in excessive accumulation." (PMID 40290126, 2025). "Furthermore, CX-5461 works in combination with PIM kinase, mTOR (everolimus), and histone deacetylase (panobinostat) inhibitors in MYC-driven cancer models, through amplifying the inhibition of ribosome biogenesis, protein synthesis, and metabolic homeostasis." (PMID 40805230, 2025). "The acetylation process represents an attractive strategy to control MYC activity in cancer cells." (PMID 40959208, 2025). "Due to the significant dysregulation of MYC and its direct involvement in the initiation and progression of cancer, it may be a feasible therapeutic approach to target MYC for the treatment of malignant tumors." (PMID 40290126, 2025). "Such opposing functions create an intricate balance that enables cancer cells to sustain elevated levels of genomic stress while maintaining survival, positioning MYC as a complex transcription factor capable of performing contradictory roles in the same cellular context." (PMID 41561634, 2025). "Moreover, the correlation between MYC suppression and clinical response to BET inhibitors was found inconsistent, as certain cancers exhibit BET inhibitor resistance despite elevated MYC expression levels." (PMID 40365020, 2025). "The phenomenon could be attributed to compensatory mechanisms or transcriptional dampening, particularly in cancer cells with deregulated MYC loci." (PMID 41303707, 2025). "In addition, we showed that F-actin is important for MYC protein expression in cancer cells on stiff ECMs." (PMID 40124511, 2025). "The results revealed that SLC35A2 might influence cancer cell metabolism through downstream molecules related to MYC, including pathways such as steroid biosynthesis, pentose phosphate pathway, and tricarboxylic acid (TCA) cycle." (PMID 40303483, 2025). "MYC, a central regulator closely involved in driving uncontrolled proliferation in cancers, including hematological malignancies, is transcriptionally regulated by NF-κB via direct effects on the promoter of both wild-type and translocated MYC." (PMID 40227701, 2025). "Similarly, MYC, a well‐established oncogene, contributes to uncontrolled cell proliferation and metabolic reprogramming in cancer." (PMID 40817807, 2025). "Additionally, lncRNA‐SNHG15 has been identified as a regulator of downstream genes such as MYC, NRAS, BAG3, and ERBB3, all of which are closely associated with cancer progression." (PMID 40620190, 2025). "However, a significant negative correlation was detected between the expression of the ST6GALNAC1 and two cancer-related biomarkers genes: MYC and POU5F1." (PMID 41152402, 2025). "~22% of KAT5-bound genes are common essential in cancer cell lines (depmap.org) and significantly overlap Myc bound genes in mouse ESCs28 and MYC and E2F-transcription factor network targets, many of which have critical roles in cell cycle entry, S-phase, and mitosis." (PMID 40346033, 2025). "Although further investigation is required to clarify the direct regulatory relationship between MED12 and MYC, our results suggest that functional loss of MED12 attenuates AKT-mediated survival signaling, thereby increasing the vulnerability of cancer cells to MEK inhibition." (PMID 40833497, 2025). "Our previous findings not only confirmed the biological relevance of MYC dosage compensation but also raised the question if miRNA sponges targeting the miR-17/92 cluster can overcome MYC dosage compensation and induce selective cytotoxicity in MYC-amplified cancer cells." (PMID 40940795, 2025). "Taken together, strategic modulation of MYC signaling pathways coupled with tailored nutritional interventions may constitute a multimodal paradigm with substantial translational potential for cancer therapeutics." (PMID 40732268, 2025). "The dual effects of MYC have also been demonstrated in other types of cancer." (PMID 40290723, 2025).
cancer (continued). "Thus, it is also critical that MYC provides cancer cells with the ability to evade immune cell recognition." (PMID 40488968, 2025). "MYC plays a role in cancer that goes far beyond driving cell division." (PMID 40076599, 2025). "Furthermore, we observed the upregulation of various cancer-associated hallmarks in cells expressing these high-risk genes, including TNF-alpha, UV response, angiogenesis, MYC, and KRAS." (PMID 40362553, 2025). "Our results presented here establish the long-sought mechanistic link between wound healing and cancer, and show that rapid proliferation during tissue regeneration and cancer uses MYC regulatory mechanisms that are genetically distinct from those used during normal homeostasis." (PMID 40180576, 2025). "Consequently, in modern cancer research, developing strategies to target MYC has gained significant attention." (PMID 40732268, 2025). "Since OC cells rely heavily on MYC to sustain their oncogenic development, MYC may be a promising therapeutic target for this challenging-to-treat cancer." (PMID 40361480, 2025). "In cancer cell lines, studies have demonstrated that genetic or pharmacological inhibition of MYC in MCF10A basal breast cells results in increased sensitivity to TGFB-stimulated invasion and metastasis, and signaling via Smad3 and ERK/Sp1 mediate TGFB-induced EGFR upregulation." (PMID 41373732, 2025). "OCT4, KLF4, SOX2, c‐MYC and other stem cell reprogramming factors play key roles in inducing stem cell formation, and many studies have shown that they can also promote the occurrence of CSCs in cancer and up‐regulate the expression of CSC markers." (PMID 40717222, 2025). "The activation of the MYC pathway is known to play a crucial role in promoting proliferative signaling, inhibiting growth inhibition, evading immune responses and cellular metabolic changes, as well as other biological processes in human cancers." (PMID 40025540, 2025). "This could make this approach highly specific for MYC-amplified cancers while preventing toxic effects on other cells." (PMID 40940795, 2025). "MYC is a key transcription factor involved in various cancer‐related pathways." (PMID 40488817, 2025). "Additionally, metabolic therapies that exploit the vulnerabilities induced by MYC, such as inhibitors of glycolysis or glutaminase, have shown preclinical efficacy in MYC-driven cancers and are now being investigated in the context of ES." (PMID 40076599, 2025). "Future studies will focus on elucidating the precise mechanism by which PA2G4 regulates MYC stability, including evaluation of MYC phosphorylation status and its regulation via the proteasome pathway in PA2G4-deficient and -proficient contexts across multiple cancer types." (PMID 41002386, 2025). "MYC is over-expressed in many human cancers and MYC-regulated transcription is highly dysregulated." (PMID 41343099, 2025). "The suppression of genes in the MYC target mechanism and their interactions with other mechanisms have been found to have a detrimental effect on cancer cells, despite the activation of the genes involved in the MTORC1 mechanism, which is important for cell growth and division." (PMID 41229448, 2025). "However, due to the extensive influence of MYC on cells, it is crucial to assess the side effects of MYC inhibition in cancer treatment." (PMID 40290126, 2025). "By narrowing the scope to MYC-related metabolic regulation, this offers a more targeted approach to therapeutic development, potentially leading to the identification of biomarkers and synthetic lethality targets to disrupt MYC-driven metabolic reprogramming in cancer." (PMID 40126351, 2025). "Gene Set Enrichment Analysis (GSEA) showed that MYC targets, mitotic spindle, G2M checkpoint, and glycolysis, all of which are hallmarks of cancer cells, were significantly activated in the Mettl3 cKO group, confirming accelerated tumorigenesis after hepatic METTL3 knockout." (PMID 40103332, 2025).
cancer (continued). "Consequently, the development of effective and safe strategies to suppress MYC expression in cancer cells remains a critical challenge." (PMID 40732268, 2025). "Furthermore, interrogating the relationship between BRG1 and MYC in SCCOHT is a critical first step to comprehending the implications of recurrent MYC target gene expression observed in multiple SWI/SNF-altered cancers." (PMID 40647552, 2025). "The expression of the MYC oncogene family is amplified in over 70% of cancers." (PMID 39796781, 2025). "Interestingly, METTL5 appears to regulate the same oncogenic target, such as MYC, across multiple cancer types." (PMID 41487998, 2025). "We also explore potential avenues for further research into how ncRNAs could be leveraged for MYC-targeted therapies, particularly in the context of synthetic lethality, offering new strategies for selectively targeting MYC-driven cancers." (PMID 40126351, 2025). "Based on these observations, we hypothesized that PVT1 genomic rearrangements, including amplifications and translocations, significantly contribute to the aggressive nature of MYC+ cancers." (PMID 40027648, 2025). "Moreover, the upregulation of ACSL4 by MYC, driven by oncogenic RTKs, increases cancer cells’ sensitivity to ferroptosis." (PMID 40732268, 2025). "Separately, BRD2/BRD4 affects oncogenes, including MYC, related to cancer." (PMID 40937321, 2025). "Studies have shown that, in order to achieve long-term resistance to L-arg deprivation therapy, cancer cells may upregulate ASS1 expression in a MYC-dependent manner." (PMID 41295280, 2025). "As expected, “MYC Targets V1” and “MYC Targets V2” pathways also showed increased NESs following MYC induction, further confirming the robustness of our framework at identifying true regulators of cancer splicing factor programs." (PMID 41101775, 2025). "Target-specific inhibition of c-MYC could represent a general therapeutic strategy for a broad spectrum of cancers." (PMID 40037707, 2025). "This strategy, which combines emerging MYC inhibitors with well-characterized metabolic drugs, provides an immediate translatable approach to improve treatment outcomes in patients with MYC-driven cancers." (PMID 40668928, 2025). "An example of the convergence of distal enhancers and cancer is the MYC oncogene." (PMID 40010352, 2025). "These limitations underscore the need to identify alternative mechanisms that regulate c-MYC expression and activity in cancer cells, which may reveal novel therapeutic vulnerabilities." (PMID 41349769, 2025). "MYC is a proto‐oncogene located in Chr8q24, which may account for the high prevalence of Chr8q24 copy number gain in cancer overall." (PMID 39917902, 2025). "MYC is a potent transcription factor that regulates essential processes such as cell growth, cell cycle progression, metabolism, and apoptosis, making it a central player in cancer biology." (PMID 40428124, 2025). "This may be in part due to the high HSF1 copy number because a previous study showed that HSF1 expression has a greater dependency on MYC in non-cancer cells." (PMID 39831777, 2025). "Therefore, inhibition of MYC in cancer cells can promote the therapeutic effect of CAR-T cells on solid tumors." (PMID 40732268, 2025). "Identifying fitness genes of MYC-driven cancers in different oxygen levels and in 3D conditions may reveal context-dependent vulnerabilities that can be exploited for therapies." (PMID 38853928, 2025). "MYC is also a potent oncogene, capable of driving various cancer hallmarks." (PMID 40487451, 2025). "The MYC transcription factor is one of the most activated oncogenes in human cancer." (PMID 39779613, 2025). "However, we have previously shown that in 98% of MYC+ cancers, MYC is co-amplified with PVT1, a long non-coding RNA (lncRNA) gene located ~30kb downstream of MYC8." (PMID 40027648, 2025). "This creates a therapeutic window in which combining MYC inhibitors with DDR-targeting agents may achieve synergistic anti-cancer effects." (PMID 41561634, 2025).
cancer (continued). "It is widely acknowledged that MYC is dysregulated in around 70% of cancer cases." (PMID 40711670, 2025). "Overexpression of c-MYC can consequently lead to transcriptional amplification in cancer cells." (PMID 39800748, 2025). "Background/Objectives: Aberrant expression of c-MYC drives aggressive cancers." (PMID 40430538, 2025). "In conclusion, our systematic framework not only reaffirms MYC as a central regulator linking cancer driver alterations to coordinated program activity but also uncovers additional candidate pathways that may contribute to this regulation." (PMID 41101775, 2025). "MYC dysregulation in most human cancers is typically not due to mutations in the MYC gene itself but rather a consequence of its activation by upstream oncogenic signaling pathways." (PMID 40966493, 2025). "Ultimately, the integration of such advanced and diverse modalities into existing MYC-targeting paradigms could significantly enhance therapeutic outcomes, bringing MYC inhibition to the forefront of next-generation cancer therapies." (PMID 40365020, 2025). "In addition, MYC is essential in the metabolism of glutamine, which is another nutrient for cancer cells." (PMID 40290126, 2025). "Understanding the crosstalk between MYC and mTOR is essential in cancer research and treatment." (PMID 39779613, 2025). "To determine whether this MYC-CoA axis also operates in human cancer, we analyzed published ChIP-seq data from a mammalian cancer model and found strong MYC occupancy at the promoters of all four PANK genes." (PMID 40832336, 2025). "MYC, a key driver of glycolysis, is commonly dysregulated across multiple cancers." (PMID 41361062, 2025). "This suggests cancer cells hijack MYC’s regulatory network to control cancer splicing programs." (PMID 41101775, 2025). "Indeed, MYC is deregulated or overexpressed in over 70% of cancers, providing them with fundamental characteristics for their survival and maintenance." (PMID 41561634, 2025). "Notably, MYC is overexpressed in more than 70% of human cancers, including lung, breast, and colorectal malignancies, often correlating with worse clinical outcomes." (PMID 40943063, 2025). "ALY/REF, in turn, is activated by c-MYC and drives cancer cell proliferation." (PMID 39514105, 2024). "By decreasing CSPG4P12 expression, CRC cells may enhance the activity of the E2F and MYC pathways, promoting uncontrolled cell division and progression of the cancer." (PMID 38808892, 2024). "Abnormal MYC gene expression is commonly observed in a variety of cancers and disabling of this gene possibly could inhibit or even stop the spread of cancer." (PMID 39281673, 2024). "The MYC gene is a major player in human cancer, making it a key driver in disease development." (PMID 38469312, 2024). "Moreover, the pro-oncogene MYC drives cancer cell growth by altering cell metabolism, leading to glutathione accumulation in Group 3 MB, which is characterized by MYC amplification." (PMID 38553479, 2024). "However, over the decades, MYC-targeted strategies against cancers have yet to see success in clinical trials due to the half-life of MYC and the rapid metabolism of the small-molecule inhibitors." (PMID 38390324, 2024). "It is also possible that U/FAS gene expression levels in cancer are, in part, regulated indirectly by MYC and MYCN through transcriptional suppression of TSmiR host gene expression and consequent release of U/FAS mRNAs from post-transcriptional TSmiR-mediated degradation." (PMID 38672672, 2024).
cancer (continued). "In addition to the important identification of RUVBL1 as a candidate for the development of an MYC-based cancer therapy, several further observations emerged from this study." (PMID 38821858, 2024). "However, in cancer, MYC and all its corollary functions are relentlessly engaged by upstream oncogenic signals to be continuously permissive for cancer initiation and/or maintenance." (PMID 38321218, 2024). "Both KRAS and MYC have been categorized as undruggable cancer targets." (PMID 39457457, 2024). "Additionally, the study sheds light on the tumorigenic capabilities of UCN and GABRD, linking these genes to pivotal pathways known to drive cancer progression, such as MYC targets V1, MYC targets V2, and DNA repair pathways." (PMID 39336730, 2024). "Pan-cancer analysis of the SLC25 family suggests that SLC25A4 is linked to multiple oncogenic pathways, including the PI3K-AKT-MTOR pathway, MYC-TARGETS-V1 pathway, MYC-TARGETS-V2 pathway, and MTORC1 pathway." (PMID 38846934, 2024). "In addition to the regulation of apoptosis, the protein products of these genes are involved in signaling pathways that are associated with cancer development and progression, including NF-ĸB (BCL3, SPHK1, and PRKCZ) and c-MYC (PIM1 and BTG1)." (PMID 38731835, 2024). "In addition, Ambra1 also promotes PP2A phosphatase dephosphorylation of MYC, destabilizing MYC and inhibiting cancer cell proliferation." (PMID 37450923, 2024). "The study also revealed that the oncogene MYC regulates the transcription of key enzymes involved in polyamine metabolism, including ornithine decarboxylase, spermidine synthase, and spermine oxidase in this type of cancer." (PMID 38187259, 2024). "In specific cancer contexts, such as LIHC, KLHL23 expression exhibited a negative association with the IL6-JAK-STAT3 signaling pathway, but a positive association with the G2M checkpoint and MYC gene targeting signaling pathway." (PMID 39636292, 2024). "In is important also to highlight that the Vk*MYC spontaneous genomic evolution and heterogenicity are in contrast to other genetically modified mouse models of cancer, where engineered expression of multiple oncogenes limits the selection for genomic diversity." (PMID 38714690, 2024). "Researchers used CRISPR-Cas9 to target the MYC gene in human cancer cells." (PMID 38195537, 2024). "This thus presents MYC as a promising therapeutic target for cancer therapy." (PMID 38390324, 2024). "Thus, the MYC-SL genes we have identified serve as valuable resource to determine strategies to indirectly, but specifically, target MYC in cancer." (PMID 38302473, 2024). "Moreover, miR-1252-5p, whose expression is suppressed by circABCB10, negatively regulates MYC, an oncogenic gene with a well-known role in cancer." (PMID 39727990, 2024). "Inactivating MYC should reduce cancer cell survival due to its role in carcinogenesis." (PMID 39563886, 2024). "Thus, further investigations have focused on identifying potential pathways through which MYC is required to drive cancer growth." (PMID 39018261, 2024). "Furthermore, several mutations at the PVT1 promoter region (obtained by published cancer human genomes), collectively highlight the importance of an intact PVT1 locus for MYC upregulation and cancer progression." (PMID 39123456, 2024). "Only a percentage of transgenic mice developed cancer from the MYC OCG after 100 days." (PMID 38827026, 2024). "Therefore, the data overall indicated that M4N was a dual inhibitor for SP1 and HIF1A and occasionally worked as an inhibitor for MYC in certain cancers." (PMID 39590335, 2024). "These undesirable site effects could have compromised the therapeutic effect of targeting MYC, as these mutations could activate BCL2L11 and thus promote cancer growth." (PMID 38195537, 2024). "OmoMYC inhibits cancer growth by forming homo-dimers as well as hetero-dimers with MYC and MAX." (PMID 38674385, 2024). "Potential MYC modulators from natural products of herbal medicine for cancer treatment." (PMID 37450923, 2024).